EPCAM (epithelial cell adhesion molecule)
Diseases named in the same sentence as EPCAM in open-access papers (continued):
Sharing a sentence is not in itself a finding about the gene and the disease.
tumor (continued). "In addition, increased numbers of EpCAM-positive tumor cells were isolated from whole blood in mice with MCF7 3C-3 tumors compared with controls, and the cells were viable and able to form colonies when grown in culture." (PMID 22632416, 2012). "Therefore, the role of EpCAM seems to depend less on the carcinoma type, and more on the respective tumor microenvironment." (PMID 23110550, 2012). "The expression of EpCAM, CD166 and CD44 in CRC is also associated with aggressive tumor phenotypes." (PMID 22267181, 2012). "The isolated EpCAM+ cells showed increased β-catenin expression compared to EpCAMˉ cells, indicating that EpCAM might be involved in the β-catenin-mediated self-renewal ability of tumor cells." (PMID 22328825, 2012). "In order to resettle and regrow which may occur in small vessels during slow down of blood flow and microthrombi formation, tumor cells seem to re-upregulate their EpCAM expression (mesenchymal-epithelial transition)." (PMID 22530147, 2012). "EpCAM may be downregulated to allow epithelial cell dissociation from the tumor, and the structural cytoplasmic CK is downregulated to facilitate cell plasticity and migration." (PMID 21577258, 2011). "For various tumour types, EpCAM overexpression has been associated with DNA hypomethylation of the promoter and treatment of EpCAM-negative cells with a DNA methylation inhibitor induced EpCAM expression." (PMID 21694727, 2011). "A fourth explanation is that all EpCAM-based detection systems could be associated with downregulation of epithelial markers - and consequently also EpCAM - in circulating tumour cells in the course of epithelial-mesenchymal transition (EMT)." (PMID 21281486, 2011). "Thus, mAb to membrane proteins overexpressed in tumors such as CD24 or EpCAM can be used to enrich tumor derived exosomes." (PMID 21651777, 2011). "Immunofluorescence analyses of sections from xenografts harvested at week 10 after tumor cell transplantation or sections of patient biopsies showed that tumors in situ have clusters of E/M cells (EpCAM+/vimentin+) as well as clusters of epithelial cells (E-cadherin+/Vimentin−)." (PMID 21264259, 2011). "Presumably, consequences of EpCAM overexpression and signaling may strongly depend on the tumour type, stage and the tumour microenvironment." (PMID 21281469, 2011). "Given the heterogeneity of circulating epithelial cells, most of which are assumed to be circulating tumor-associated epithelial cells, the question of detection specificity has not been well studied beyond the parameters of EpCAM and CK." (PMID 21577258, 2011). "EpCAM expression was significantly increased in tumours with perineural invasion (p = 0.050)." (PMID 21281486, 2011). "However, neither the basal secretion of IL-6 nor the induced secretion of IL-6 by PGE2 in fibroblasts correlated with fibroblast tumor promoting ability in vivo or their ability to expand CD44+/CD24−/EpCAM+ cells in vitro." (PMID 21957456, 2011). "EpCAM is the functionally evaluated molecule for a role in tumor cell invasion and proliferation." (PMID 20844677, 2010). "The nature of invading cells was further corroborated upon staining for the tumour-associated antigen EpCAM (data not shown)." (PMID 20222943, 2010). "Overexpression of full-length EpCAM or EpICD in quiescent cells elicits tumor formation." (PMID 20976159, 2010). "Loss, rather than overexpression, of membranous CD44s, CD166, and EpCAM is linked to tumour progression." (PMID 20606680, 2010). "Primary tumor tissues, in general, showed a different spectrum of cellular heterogeneity compared to breast reduction mammoplasty tissue by flow cytometry when stained for EpCAM, CD49f, and CD24." (PMID 20964822, 2010). "This therapeutic goal may be achieved by developing robust high throughput assays on clinical tumor tissue samples for these two EpCAM components to serve as a guide to target monoclonal antibody therapy." (PMID 21152431, 2010).
tumor (continued). "EpCAM is one of the most widely investigated proteins in human cancers, frequently overexpressed in human malignancies, localized on the plasma membrane of tumor cells and albeit at lower levels in the normal epithelia." (PMID 21152431, 2010). "The regulation of EpCAM in tumour invasion and metastasis has previously been reviewed." (PMID 21339979, 2010). "EpCAM has been extensively studied as a potential tumor marker and immunotherapy target, and more recent studies suggest that EpCAM expression may be characteristic of cancer stem cells." (PMID 20046825, 2009). "In case neighbouring cells are missing, like it is e.g. the case for disseminated tumour cells, cells might decrease levels of EpCAM activation, receive less proliferation signals, and might rest in a state of quiescence (condition D1)." (PMID 19925656, 2009). "Because CK and EpCAM are both heterogeneously expressed on tumor cells, the enrichment with the combined antibodies may increase the sensitivity and reproducibility by the compensation effect of biomarkers from each other." (PMID 18687126, 2008). "Subsequent oligomerisation of EpCAM may then provide a constitutive proliferation signal for tumour cells." (PMID 17211480, 2007). "Furthermore, we discuss the impact of the binding kinetics with respect to immunotherapy of EpCAM-positive tumours by conventional monoclonal vs trifunctional antibodies." (PMID 17622246, 2007). "Patients without loss of EpCAM expression of tumour cells (19%) had a significantly better 10-year survival compared with patients with any loss: 42 vs 22%." (PMID 17325709, 2007). "Ongoing studies are investigating a role of EpCAM as membrane-bound protease inhibitor, a function that may serve to protect tumour cells from their own secreted cathepsins during metastasis." (PMID 17211480, 2007). "The question of whether anti-EpCAM antibodies directly inhibit tumour cell proliferation remains unanswered." (PMID 17325709, 2007). "Interestingly, a recent study revealed a 10-fold reduction in the expression of EpCAM in circulating tumour cells compared with primary tumours from whence they emerged and established metastases." (PMID 17325709, 2007). "The most important insights into the accessibility of EpCAM on normal epithelia vs tumour cells may come from recent studies identifying a number of other proteins found in close association with EpCAM within the cell membrane." (PMID 17211480, 2007). "The mechanisms by which anti-EpCAM antibodies exert tumour inhibition in vivo remain controversial." (PMID 17325709, 2007). "Although epithelial cell adhesion/activating molecule (EpCAM/CD326) is one of the first tumour-associated antigens identified, it has never received the same level of attention as other target proteins for therapy of cancer." (PMID 17211480, 2007). "Use of EpCAM targeted immunotherapy earlier in disease progression may enhance tumour penetration and delivery to target cells in solid tumours." (PMID 17325709, 2007). "In conclusion, the application of high-affinity and effective trAbs administered locally at very low concentrations may re-open the therapeutic window for immunotherapy of EpCAM expressing tumours." (PMID 17622246, 2007). "Tissue microarray studies allow comprehensive assessment of the tumour expression of EpCAM." (PMID 17325709, 2007). "The new insights into membrane protein complexes containing EpCAM may be the key to understand both the control of EpCAM signalling in normal vs tumour tissue and the basis for a therapeutic window of some but not all EpCAM-directed immunotherapies." (PMID 17211480, 2007). "A novel EpCAM-directed immunotoxin is under development that has the furin cleavage site replaced by a site cleaved through matrix metalloproteinases-2 and -9, as are selectively expressed by tumour cells." (PMID 17211480, 2007). "The two binding sites of this antibody are against EpCAM positive tumor cells and T cells (CD3+)." (PMID 17125516, 2006).
tumor (continued). "The epithelial origin of the tumor cells was proven by morphological criteria including the presence of mucin within the cells and the expression analysis of protein commonly expressed in epithelial cells (EpCAM, E-cadherin, CEACAM1)." (PMID 16536871, 2006). "However, whether EPCAM+ sEV can be specifically secreted by tumor cells of TC and serve as a biomarker for TC remains uncovered." (PMID 41551611, 2025). "Thus, the presence or absence of EpCAM expression in tumor cells, including CTCs, cannot be linked to the malignant traits of tumor cells." (PMID 40699639, 2025). "Nonetheless, the LPCTC-iChip platform used here is also adaptable to a “positive selection” mode, including the capture of CTCs by virtue of their expression of EpCAM or other epithelial or tumor-specific epitopes, which may be valuable in specific tumor-targeting contexts." (PMID 39746954, 2025). "Also, during tumor progression, dynamic changes in EpCAM expression occur, prompting the use of enrichment systems that enable the simultaneous investigation of both EpCAM+ and EpCAM− CTCs to gain a more comprehensive understanding of EpCAM’s role in tumor progression." (PMID 39996844, 2025). "Finally, (tumor) epithelial cells were distinguished via EpCAM." (PMID 39808498, 2025). "Nonetheless, cancer-associated macrophage-like cells (CAMLs), which may also be identified as hybrids due to their multinucleated structure and expression of CD14+, CD45+, cytokeratin+, and EpCAM+ markers, have been observed to cluster with CTCs at primary tumour sites." (PMID 39967663, 2025). "To verify whether monocyte- and macrophage-CM modulate the tumor plasticity of SCC cells, we analyzed the expression of genes associated with epithelial-mesenchymal transition (EPCAM, SOX2), stemness (NANOG, MYC, EZH2), and neuroendocrine differentiation (CHGA, AURKA, MYCN)." (PMID 41259557, 2025). "However, EpCAM’s prognostic value varies depending on the tumor type." (PMID 40445498, 2025). "However, the overall enrichment of EpCAM+ tumor cells remained suboptimal." (PMID 40525275, 2025). "So, this EpCAM epitope may contribute to the potent anti-tumor effect of our new anti-EpCAM sdAbs." (PMID 40017594, 2025). "Additionally, the tumor sample contained various other cell types, including epithelial cells (EPCAM+), pStr (MKI67+) CD4+T cells (CD4+), CD8+ T cells (CD8A+), macrophages (CD68+), and regulatory T cells (FOXP3+), which were further validated by our single-cell data." (PMID 39676856, 2024). "However, the expression of EPCAM has high heterogeneity and different dynamics among different types of epithelial tumor cells, and the transliteration of epithelial intermediate transformation (EMT) may reduce the expression level of EPCAM and CKS18." (PMID 38830909, 2024). "Our investigation indicates that patients with diminished EpCAM expression may experience enhanced therapeutic efficacy when treated with immune checkpoint inhibitors, ultimately bolstering the immune response against the tumor." (PMID 38187284, 2024). "This indicates that EpCAM may promote EMT to facilitate tumor metastasis." (PMID 38791091, 2024). "Using EpCAM-magnetic beads, we achieved sorting and sectional capture of target cells in whole blood and analyzed the surface expression levels of the captured cells, confirming the functionality of the microfluidic chip in sorting and capturing subtypes of circulating tumor cells." (PMID 38675353, 2024). "Plasma EVs with EpCAM and CD44V6 also have a prognostic role in PDAC, with the former’s levels being associated with the treatment response during systemic, palliative chemotherapy in advanced PDAC cases, as well as with the tumor stage, whereas the latter’s are only related to the tumor stage." (PMID 38542378, 2024).
tumor (continued). "This is seemingly at odds with recent research into CTC-based PDAC prognostics whereby several groups identified CTCs adopting a mesenchymal EpCAM-negative phenotype were associated with poorer prognosis, consistent with the invasive characteristics associated with mesenchymal tumour cells." (PMID 39409954, 2024). "Consequently, a decreasing amount of EpCAM-directed CAR T-cell was paralleled by tumor growth." (PMID 39358663, 2024). "Notably, the tumor uptake level correlated with the expression of EpCAM in tumor biopsy samples." (PMID 39199590, 2024). "In addition, fewer EpCAM+ epithelial cells indicated a reduction in tumor cellularity." (PMID 38516270, 2024). "Anti-EpCAM 9C4 mAb staining provided a strong and specific signal from morphologically characteristic ductal and exocrine epithelial cells in all analyzed samples of normal and tumor tissues that could be imaged using both WFM and FOM." (PMID 38883274, 2024). "In addition, EPCAM knockdown in LMS cell lines reduced tumour cell migration in vitro." (PMID 38291183, 2024). "Under normal conditions, EpCAM is involved in cell-cell adhesion and the regulation of differentiation in progenitor and embryonic stem cells; however, in the context of cancer, EpCAM overexpression is related to increased cell proliferation, migration, invasion, and tumor metastasis." (PMID 37175871, 2023). "We inferred that VH-F12 might have an anti-tumour effect by inhibiting the glycosylation of EpCAM." (PMID 37834237, 2023). "We have shown in this study that the majority of CRC in our population preferentially overexpress EpCAM over E-cadherin and this favours local tumour progression by conferring more invasive properties to the tumour cells even among E-cadherin-expressing tumours." (PMID 37533952, 2023). "Smarcd3 deletion led to a greater significant loss (3-fold) in EpCAM+ tumor cells, and a 3.5-fold reduction in EpCAM+MSI2+ tumor stem cells in secondary transplants, suggesting that Smarcd3 deletion reduces the self-renewal capability of established tumor cells." (PMID 36653361, 2023). "A murine EpCAM CAR T cell study provided counterevidence that these cells may cause lethal toxicity, as cell infusion resulted in dose-dependent cytokine release syndrome, weight loss, and death in tumor-bearing and tumor-free mice." (PMID 38067366, 2023). "To test whether the higher resistance of EPCAM− tumour cells to chemotherapy is related to the higher ability to cope with replicative stress, we evaluated the sensitivity of EPCAM+, EPCAM− and Rhoj-KO tumour cells to the replicative-stress-inducing drug aphidicolin." (PMID 36949199, 2023). "Both murine SCC VII and primary human tumor cells collected from patients with HNSCC responded similarly in vitro to Rho kinase inhibition, which promoted a CD44hi tCSC phenotype additionally associated with coexpression of other stem cell markers including ALDH1A1, EpCAM, and EGFR." (PMID 37655661, 2023). "Furthermore, while invading myoepithelial cells were Vimentin positive, luminal cells maintained expression of the epithelial specific marker EpCAM, demonstrating collective invasion and maintenance of the epithelial phenotype observed in tumour invasion 33–36." (PMID 36864079, 2023). "Finally, we established subcutaneous xenotransplanted tumor models of CD44+EpCAM (high) cells." (PMID 36765401, 2023). "We observed a close clonal relationship of EpCAM high-expressing and low-expressing CTCs, as well as EpCAM dependently and independently enriched CTCs on the level of chromosomal aberration, indicating that both fractions of CTCs represent similar subclones of the tumour lesions." (PMID 36823365, 2023). "Recently, a multivariate analysis of EpCam expression in CRC by immunohistochemistry has demonstrated that its downregulation represents an independent prognostic factor associated with poor disease-specific survival and is associated with an increase in the migratory capacity of the tumor cells." (PMID 37370706, 2023).
tumor (continued). "Therefore, enhancement of the anti-tumor effects of EpCAM-directed antibody therapy is needed." (PMID 36918661, 2023). "We hypothesized that larger EpCAM-positive EVs with a higher number of EpCAM molecules can bind more effectively to tumor-reactive autoantibodies and to therapeutic EpCAM antibodies and thereby reduce the binding of antibodies to tumor cells." (PMID 37375854, 2023). "To validate the inhibitory role of CD47 expression in neutrophil-mediated killing of tumor cells, we screened a large number of tumor cell lines and evaluated the expression levels of common tumors associated antigen targets, including CD47, as well as the expression of EGFR, EpCAM, and HER2." (PMID 37444515, 2023). "Associations were not seen between EpCAM staining levels and overall or tumor specific survival." (PMID 38282671, 2023). "In fact, even if EVs constitute only approximately 0.005% of the volume of blood plasma, tumor-derived EVs may be isolated from biofluids using tumor-specific or tumor-enriched surface markers (e.g., EpCAM), allowing the analysis of biospecimen enriched in tumor-specific cargo." (PMID 36839759, 2023). "Importantly, in FACS analysis, despite variability in the median fluorescence intensity across the models tested (n = 9), EpCam+ tumor cells homogenously expressed B7H3 (80%–100% cells) at the cell surface, which makes B7H3 an ideal target for ADC based therapy." (PMID 37725435, 2023). "Patients whose tumours express EpCAM might benefit from anti-EpCAM targeted therapy." (PMID 37533952, 2023). "Besides, in a colorectal cancer xenograft model, tumor progression was significantly blocked by EpCAM‐CAR‐T‐cell administration, followed by the increase of cytotoxic cytokines, including interferon‐γ (IFN‐γ) and tumor necrosis factor‐alpha (TNF‐α) that were confirmed via in vitro evaluation." (PMID 37698048, 2023). "It is believed that CD45−/EpCAM+/CK+ cells in peripheral blood are CTCs, and their status is closely related to the clinical stage, lymph node metastasis, degree of differentiation, and prognosis of tumor patients and plays an important role in tumor recurrence, metastasis, and prognosis evaluation." (PMID 36131792, 2022). "Alternatively, classification of EpCAM+EGFR+ events as tumor cells could be unjustified." (PMID 36613466, 2022). "This means that EpCAM-specific antibodies are conjugated with cytotoxic agents, such as doxorubicin, paclitaxel, calicheamicin, topoisomerase I inhibitors, alpha amanitin, and indolinobenzodiazepine pseudodimers (IGNs), to specifically kill the EpCAM+ tumor cells." (PMID 35986321, 2022). "Finally, one must realise that tumor cells expressing EpCAM may undergo epithelial mesenchymal transformation with a reduction of EpCAM expression." (PMID 35890293, 2022). "The ex vivo approach described here with the purification of different cell types (EpCAM/CD49f) prior to adenovirus treatment could be used to definitively identify the cell of origin and study how the cell of origin impacts tumor formation, progression, and immunotherapy responses." (PMID 35626115, 2022). "Indeed, tumor cell spheroids are formed with epithelial adhesion by E-cadherin and EpCAM while simultaneously expressing mesenchymal marker vimentin, indicating that a hybrid/partial EMT status may be essential for tumor and spheroid formation." (PMID 36552758, 2022). "An alternative approach that could have been taken would have been to ‘fish out’ EVs of epithelial origin from the bulk of the EVs in the plasma samples (assuming that tumour EVs express EpCAM to a high degree) and subsequently use this amount of EVs for normalisation of the samples." (PMID 35838333, 2022). "Tumor-associated EVs extensively circulate in biological fluids of cancer patients, and it is conceivable that high levels of blood-derived CD133+ and EPCAM+ EVs in patients with mCRC might be related with an increased secretion of these EV subtypes by cancer cells." (PMID 35267665, 2022).